ABCB1 (ATP binding cassette subfamily B member 1)
Diseases named in the same sentence as ABCB1 in open-access papers (continued):
Sharing a sentence is not in itself a finding about the gene and the disease.
melanoma (continued). "Further, we and others have shown a direct effect of GH–GHR action in upregulating expression of ATP-cassette-containing (ABC) multidrug efflux pumps such as ABCB1, ABCC1, ABCC2, and ABCG2 in melanoma as well as in breast cancer." (PMID 31547367, 2019). "It was previously shown that GH action in GHR+ human melanoma cells upregulates while GHR knockdown suppresses the ABC-transporter system, especially ABCB1, ABCB5, ABCB8, ABCC1, ABCC2, ABCG1, and ABCG2 differentially in a drug-dependent manner." (PMID 31547367, 2019). "PLX4032 and PLX4720 also sensitised two wild-type BRAF melanoma cell lines, IPC-298 and SK-Mel-30 (DSMZ, Braunschweig, Germany), that express ABCB1, ABCC1, and ABCG2 to vincristine and mitoxantrone." (PMID 25300205, 2014). "Here, we investigated the role of the ABC transporters ABCB1, ABCC1, and ABCG2 during melanoma cell resistance acquisition to the V600-mutant BRAF inhibitors PLX4032 (vemurafenib) and PLX4720." (PMID 25300205, 2014). "In further support, the melanoma SP shows upregulated expression of factors that by others have been assigned to (candidate) melanoma CSC, including ABCB1, DNMT3B, EPAS1, JARID1B and TERT." (PMID 24098529, 2013). "Additionally, we showed that the protein levels of ABCC1, ABCC2, ABCB1, and ABCG2 were elevated in presence of GH treatment in parent melanoma cells (Malme-3M and SK-MEL-28)." (PMID 39123364, 2024). "In melanoma cells with HSF1 overexpression, upregulation of ABCB1 gene transcription was prominent." (PMID 37958341, 2023). "A query of human tumor transcriptomic data for 471 melanoma patients from The Cancer Genome Atlas (TCGA) dataset revealed a positive correlation of IGF1 and ABCC9, ABCG1, ABCB1, and ABCC4 with GHR expression, and ABCC1 with both GHR and IGF1R expression, supporting our observations." (PMID 35865483, 2022). "In melanoma metastases, single or clustered ABCB1+ cells were only found disseminated over the tumor (and not localized in a front)." (PMID 24098529, 2013). "Although the authors of the study did not characterize the stem cell markers in melanoma, based on the data obtained, a cautious conclusion can be drawn that pravastatin promotes the increase in the activity of the ABCB1 channel and thus, indirectly, tumour growth." (PMID 38136555, 2023). "Interestingly, ABCB1, ABCG2, ABCB5 and ABCC1 have been found important in melanoma chemoresistance." (PMID 24098529, 2013). "A similar, but not significant, increase in ABCB1 and ABCG2 was observed in the melanoma recipient cells when administered with ExoGH, Exodoxo, and ExoGH+doxo as compared with the controls." (PMID 39123364, 2024). "Melanoma cell response to CCT018159 was independent of NQO1 expression and the level of P-glycoprotein/ABCB1 (ATP binding cassette subfamily B member 1) involved in drug efflux." (PMID 31659567, 2020).
acute myeloid leukemia (51 papers, 1994 to 2026). Acute myeloid leukemia (AML) is a group of neoplasms arising from precursor cells committed to the myeloid cell-line differentiation. "This study aims to determine the frequency of ABCB1 gene polymorphism C3435T (rs1045642) in acute myeloid leukemia patients at tertiary care hospitals in Lahore, Pakistan." (PMID 41520507, 2026). "This study suggests that the TT genotype of the ABCB1 C3435T gene polymorphism is more strongly associated with acute myeloid leukemia compared to controls." (PMID 41520507, 2026). "A cross-sectional comparative study was conducted to investigate the association between ABCB1 gene polymorphism (C3435T) and acute myeloid leukemia." (PMID 41520507, 2026). "We have shown that the development of drug resistance associated with ABCB1 overexpression leads to decreased regulation of latrophilin-1 in human acute myeloid leukemia cell lines." (PMID 34298843, 2021). "Chemotherapeutic drug efflux via the P-glycoprotein (P-gp) transporter encoded by the MDR1/ABCB1 gene is a significant cause of drug resistance in numerous malignancies, including acute leukemias, especially in older patients with acute myeloid leukemia (AML)." (PMID 18271955, 2008). "In the case of ABCB1 rs1045642 and rs1128503 variants, the identification of a lower frequency of the AA haplotype in the Chilean population has potential implications for drug responses and toxicity, especially in the context of acute myeloid leukemia." (PMID 38675222, 2024). "Resistance to chemotherapy is the most common cause of treatment failure in acute myeloid leukemia (AML) and the drug efflux pump ABCB1 is a critical mediator." (PMID 33167906, 2020). "As previously reported, the immature KG1 acute myeloid leukemia cell line overexpressed LSC-associated and ABCB1 genes and made up an important CD34 + CD38− LSC subpopulation (10.4%)." (PMID 35628366, 2022). "Research indicated that Cav-1 expression was positively correlated to ABCB1 in various cancers such as acute myeloid leukemia." (PMID 26431273, 2015). "Clinical evidence has shown that high expression of ABCB1 and/or ABCG2 is linked with the MDR phenotype in advanced NSCLC, metastatic breast cancer, acute lymphocytic leukemia (ALL), acute myelogenous leukemia (AML), chronic lymphocytic leukemia (CLL), and multiple myeloma (MM)." (PMID 37048130, 2023). "Furthermore, we provided the evidence that in case of ABCB1 overexpression in human acute myeloid leukemia cell lines, changes in the expression of latrophilin-1-regulated proteins occur that are thought to allow myeloid blasts to escape control of the immune system." (PMID 34298843, 2021). "A clinical study performed in 2006 to evaluate the gene expression of adult acute myeloid leukemia (AML) showed high MDR1/ABCB1 and BCRP/ABCG2 expression in a subset of patients with the worst overall survival and high drug resistance." (PMID 34208283, 2021). "High expression of ABCB1 and ABCG2 has been associated with reduced chemosensitivity and MDR phenotype in blood cancers such as MM, chronic lymphocytic leukemia (CLL), acute lymphocytic leukemia (ALL), and acute myelogenous leukemia (AML), as well as solid tumors such as metastatic breast cancer." (PMID 33807514, 2021). "P-glycoprotein (known as ABCB1 transporter) expression in myeloid blasts of acute myeloid leukemia (AML) or myelodysplastic syndrome (MDS) leads to the commonly observed multidrug resistance." (PMID 34298843, 2021). "The drug efflux pump ABCB1 is a key driver of chemoresistance, and high expression predicts treatment failure in acute myeloid leukemia (AML)." (PMID 31770110, 2020). "In a study involving Colombian children with acute myeloid leukemia (AML), the combination of ABCB1 rs1128503, rs2032582, and rs1045642 AA/AA/AA was strongly associated with death after hematopoietic stem cell transplantation, demonstrating an odds ratio of 13.73." (PMID 38675222, 2024).
acute myeloid leukemia (continued). "We analyzed the expression of BCL2, BAX, and ABCB1 in bone-marrow samples collected at diagnosis from 51 adult patients with acute myeloid leukemia with normal karyotype (AML-NK) using real-time polymerase chain reaction method, and examined their prognostic potential." (PMID 37078709, 2023). "In acute myeloid leukemia patients, repeat exposure to daunorubicin has been shown to induce the ISR and ATF4 expression, resulting in increased drug efflux, via ATP binding cassette subfamily B member 1 (ABCB1), and treatment failure." (PMID 33525628, 2021). "High level expression of the drug efflux pump ABCB1 leading to active efflux from blast cells of standard-of-care chemotherapy drugs such as daunorubicin and cytarabine is one of the strongest predictors for induction failure in acute myeloid leukemia (AML)." (PMID 33167906, 2020). "ABCB1 is a member of the ATP binding cassette transporter family and high ABCB1 activity is considered as a poor prognostic factor in acute myeloid leukemia (AML) treated with intensive chemotherapy, its direct relation with drug resistance remains unclear." (PMID 31500210, 2019). "For example, VAL was shown to increase ABCB1 expression and function in human colon adenocarcinoma cell line SW620 and acute myelogenous leukaemia KG1a cells." (PMID 28961159, 2017). "Corroborating these data, it has been recently described that co-culture with mesenchymal stromal cells from bone marrow induced increased activity of ABCB1, ABCG2 and ABCC1 with the development of an SP phenotype from blasts of acute myeloid leukemias obtained from human patients." (PMID 37047018, 2023). "Clinical studies indicated a positive correlation between Cav-1 and ABCB1 mRNA in acute myeloid leukemia independent of tumor stage." (PMID 26431273, 2015). "Recently, a phase III trial of the potent and specific ABCB1 inhibitor zosuquidar reported that this drug did not improve the outcome of older patients with newly diagnosed acute myeloid leukemia." (PMID 25268163, 2014). "In acute myeloid leukemia, as well as in many other cancer types, a recognized role in affecting the initial response to chemotherapy has been attributed to the efflux pump activity of the tree most studied members of the ABC protein family, ABCB1, ABCC1, and ABCG2." (PMID 38255216, 2024). "However, our findings, along with published data, suggest that ABCB1 could be considered a prognostic factor for CML, as it is in acute myeloid leukemia." (PMID 22458888, 2012).
glioblastoma (51 papers, 1992 to 2026). The most malignant astrocytic tumor (WHO grade IV). "The ABCB1 3435CC genotype is associated with a 37% survival rate in glioblastoma patients after a temozolomide treatment." (PMID 36432633, 2022). "For ABCB1, as much as ~4% of the glioblastoma patients carried mutations and another 2.5% of the patients carried amplification of the gene (TCGA)." (PMID 29186899, 2017). "In certain glioblastomas, high expression of ABCB1 and ABCG2 has been reported to associate with poor prognosis." (PMID 29186899, 2017). "Expression of miR-9, in U87 and T98G glioblastoma cell lines, was associated with increased amounts of ABCB1 and ABCG2 mRNA and protein." (PMID 29186899, 2017). "Transfecting U87 glioblastoma cells with synthetic miR-145 decreases both ABCB1 and ABCG2 protein levels, which in return increases sunitinib cytotoxicity." (PMID 36973040, 2023). "Another miRNA, miR-4539, altered expression of ABCB1 in T98G glioblastoma cells and aligned strongly with the 3′-UTR mRNA sequence of ABCB1." (PMID 36973040, 2023). "In glioblastoma, ABCB1 protein expression levels, measured with Western blotting and immunohistochemistry, were increased in patient samples from the second resection compared with those from the first resection." (PMID 36973040, 2023). "The effects of TMZ treatment on U87 cell viability and resistance-related gene expression (MGMT and ABCB1) were used to validate and compare our long-term 3D with 2D glioblastoma cell culture." (PMID 34439644, 2021). "Our results demonstrated that besides MGMT, ABCB1 expression also increases in 3D glioblastoma cell culture more profoundly than in 2D." (PMID 34439644, 2021). "Our previous study showed that SFK inhibitors Si306 and its prodrug pro-Si306 suppress the P-gp (ABCB1) transporter activity in MDR glioblastoma cells." (PMID 34771471, 2021). "On the other hand, an ABCB-1 blocker, elacridar, increases treatment efficacy in glioblastoma patients by overcoming blood-brain barrier." (PMID 32041631, 2020). "The alkylating agent TMZ is the drug of choice in treating glioblastoma and the contribution of ABCB1 and ABCG2 to its efficacy has been widely studied." (PMID 29186899, 2017). "Strikingly, a link between ABCB1 and glioblastoma treatment efficacy came from an analysis of ABCB1 SNPs in TMZ-treated glioblastoma patients." (PMID 29186899, 2017). "CSCs isolated by forming spheroid cultures of glioblastoma tumor cells were previously shown to have high expression of ABCB1 gene and were found to be significantly resistant to chemotherapeutic agents." (PMID 24391839, 2013). "In summary, our study represents a combined investigation of promoter methylation and gene polymorphisms of the pivotal drug resistance genes MGMT, ABCB1 and ABCG2 in glioblastoma multiforme." (PMID 24380367, 2013). "Our data argue against any relevant impact of MGMT, ABCB1 or ABCG2 promoter methylation on overall survival of glioblastoma patients." (PMID 24380367, 2013). "ABCB1 was shown to be expressed both in low-grade glioma and high-grade glioma such as glioblastoma and ABCG2 was found to be expressed in glioma stem cells as well as in endothelial cells of the large vessels of glioma tissue." (PMID 24380367, 2013). "To date, no study analyzing ABCB1 promoter methylation and its relation to ABCB1 expression and OS of glioblastoma patients is reported." (PMID 24380367, 2013). "This out-group consisted of ABCB1, which encodes the efflux transporter P-glycoprotein, a well-known inducer of multidrug resistance, and GJA1, a gap junction component involved in chemoresistance regulation of glioblastoma cells." (PMID 41153808, 2025). "The increase in ABCB1 expression in glioblastoma patient samples may be mainly due to increased expression at the blood-tumor barrier, and transporter expression levels in tumor cells seem to play a minor role in drug resistance." (PMID 36973040, 2023).
glioblastoma (continued). "Ibudilast sensitised glioblastoma cells to temozolomide by inhibiting the macrophage migration inhibitory factor, while sildenafil is included on the basis of its ability to inhibit drug transporters ABCB1 and ABCG2." (PMID 34575827, 2021). "However, the transcriptional pattern of the ABCB1 gene varies between MDR glioblastoma and NSCLCs, suggesting that regulation may occur at the post-transcriptional level." (PMID 40006556, 2025). "We took advantage of the publicly available databases to evaluate whether ABCB1 and ABCG2 genes were altered, by mutation or amplification, in CNS tumors, glioblastoma and medulloblastoma (the most common pediatric CNS tumor- will be described in details later)." (PMID 29186899, 2017). "However, some TMZ-resistant glioblastoma cells exhibit increased levels of ABCB1 and ABCG2." (PMID 29186899, 2017). "HIF-1α, a transcriptional regulator of ABCB1, also exhibited a different pattern in MDR glioblastoma and NSCLCs that mirrors ABCB1 expression." (PMID 40006556, 2025). "We therefore investigated promoter methylation of ABCB1 and ABCG2 in 64 glioblastoma patients using the pyrosequencing technology, which allows unequivocal quantification of the methylation status, and used MGMT promoter methylation as positive control." (PMID 24380367, 2013). "However, we could detect a significant negative correlation between MGMT promoter methylation and MGMT expression, a markedly elevated MGMT and ABCB1 promoter methylation in glioblastoma specimens and a significant correlation between MGMT methylation and the MGMT C-56 T polymorphism." (PMID 24380367, 2013). "PPARγ also regulates ABCB1 and ABCG2 in human glioblastoma cell lines in vitro." (PMID 36973040, 2023). "Thus, we focused on establishing new pyrosequencing assays for the analysis of the methylation status of the ABCB1 and the ABCG2 promoter in a collective of 64 glioblastoma patients using MGMT promoter methylation as reference." (PMID 24380367, 2013). "However, the ABCB1 methylation measured in 64 GBM patients was significantly higher than in the controls (Mann Whitney test p = 0.007), suggesting a different epigenetic regulation in glioblastomas than in healthy brain." (PMID 24380367, 2013). "By improving the physicochemical properties of GDC-0941, such that it bypassed ABCB1 and ABCG2 efflux, GNE-317 (an improved version of GDC-0941) effectively decreased tumor growth in all glioblastoma models tested, regardless of the BBB integrity and function." (PMID 29186899, 2017). "To study a correlation between promoter methylation and gene expression, we analyzed MGMT, ABCB1 and ABCG2 expression in 20 glioblastoma and 7 non-neoplastic brain samples." (PMID 24380367, 2013). "In glioblastoma patients, currently available EGFR inhibitors do not provide a survival benefit but could be used to overcome blood-brain barrier ABCB1/ABCG2-mediated drug resistance via transporter internalization/degradation." (PMID 36973040, 2023). "ABCB1 and ABCG2 promoter methylation have not been assessed in glioblastoma patients before." (PMID 24380367, 2013). "However, in contrast to MGMT methylation no data have existed for ABCB1 and ABCG2 promoter methylation in glioblastoma tissue until now." (PMID 24380367, 2013).